CD36 (CD36 molecule (CD36 blood group))
Diseases named in the same sentence as CD36 in open-access papers (continued):
Sharing a sentence is not in itself a finding about the gene and the disease.
CD36 also shares sentences with these, for which no sentence is quoted: acute myocardial infarction (5 papers); dilated cardiomyopathy (5); atrial fibrillation (4); renal carcinoma (4); infectious disease (3); lung squamous cell carcinoma (3); acquired immunodeficiency syndrome (2); acute lung injury (2); cholestasis (2); chronic hepatitis C (2); epilepsy (2); esophageal squamous cell carcinoma (2); essential hypertension (2); fibrosis (2); hepatic (2); hypertrophy (2); leishmaniasis (2); Lewis Lung Carcinoma (2); lipodystrophy (2); metastatic melanoma (2); neovascular age-related macular degeneration (2); Obstructive Sleep Apnea (2); osteoarthritis (2); Parkinson disease (2); pneumococcal infection (2); Polypoidal choroidal vasculopathy (2); prostatic intraepithelial neoplasia (2); psoriasis (2); schistosomiasis (2); thyroid cancer (2).
A further 105 diseases each share a sentence with CD36 in 2 papers or fewer.